PGR (progesterone receptor)
Diseases named in the same sentence as PGR in open-access papers (continued):
Sharing a sentence is not in itself a finding about the gene and the disease.
breast cancer (continued). "Triple-negative breast cancer (TNBC) is a subtype of breast cancer that is characterized by the lack of estrogen receptor (ER), progesterone receptor (PR), and human epidermal growth factor receptor 2 (HER2) expression." (PMID 38213533, 2023). "In addition, combined with the oestrogen receptor (ER), the progesterone receptor (PR), Ki-67, CK5/6, and the epidermal growth factor receptor (EGFR), HER2 plays an important role in the molecular classification of breast cancer." (PMID 37328516, 2023). "About one-third of patients with estrogen receptor alpha (ERα)-positive breast cancer have tumors which are progesterone receptor (PR) negative." (PMID 37550554, 2023). "Triple-negative breast cancer (TNBC) accounts for 10–15% of breast cancer cases and is a subtype characterized by the lack of estrogen receptor (ER), progesterone receptor (PR), and human epidermal growth factor receptor 2 (HER2) expression/amplification." (PMID 36385236, 2023). "The status of ER, PgR, AR, PD-L1 (hPD-L1), and TIL (hTIL) in breast cancer tissue was histologically evaluated by IHC and H&E staining using the samples obtained at our facility from 45 patients with breast cancer." (PMID 36721218, 2023). "The triple-negative (ER-, PgR-, and HER2-negative) subtype of breast cancer was reported to have a poor prognosis compared to luminal (ER-positive and/or PgR-negative and HER2-negative) breast cancer." (PMID 37163537, 2023). "Particularly, TNBC accounts for 5–25% of all breast cancers and is a clinical estrogen receptor (ER), progesterone receptor (PR), and human epidermal growth factor receptor 2 negative tumors." (PMID 38202691, 2023). "In comparative medicine, veterinary researchers have applied the immunophenotypes adopted from human breast cancer (HBC) to CMT using protein biomarkers such as estrogen receptor (ER), progesterone receptor (PR), and human epidermal growth factor receptor 2 (HER2)." (PMID 36717813, 2023). "Triple-negative breast cancer subtype is negative for estrogen receptor (ER), progesterone receptor (PR), and human epidermal growth factor receptor 2 (HER2)." (PMID 37687058, 2023). "TNBC is a notorious subtype of breast cancer lacking estrogen receptor, progesterone receptor, and human epidermal growth factor receptor‐2 overexpression, accounting for 10%–24% of all breast cancers." (PMID 38089401, 2023). "In the clinic, the treatment strategy for breast cancer is determined by the presence or absence of three receptors: the estrogen receptor (ER), progesterone receptor (PR), and the human epidermal growth factor receptor (HER2)." (PMID 37394063, 2023). "The lack of oestrogen receptor, progesterone receptor and human epidermal growth factor receptor-2 expression in breast cancer (BC) is the basis for the categorization of the tumour as triple negative breast carcinoma (TNBC)." (PMID 37012444, 2023). "Consistent with this line of investigation, we have previously shown that C1QBP is a proliferative marker in breast cancer tissue samples, and depletion of C1QBP protein in other breast cancer sub-types such as progesterone receptor positive T47D cells decreased cell proliferation and growth." (PMID 36674861, 2023). "Triple-negative breast cancer (TNBC) is a molecular subtype of breast cancer (BC) lacking the expression of the estrogen receptor (ER), progesterone receptor (PR), and human epidermal growth factor receptor-2 (HER2)." (PMID 37749101, 2023). "Triple-negative breast cancer (TNBC) represents a highly aggressive and heterogeneous subtype of breast cancer (BC), characterized by the absence of estrogen receptor (ER), progesterone receptor (PgR), and HER2 expression." (PMID 37511789, 2023). "Triple-negative breast cancer (TNBC) is a subtype of breast cancer characterized by lack of an estrogen receptor (ER), progesterone receptor (PR), and HER2 expression, with a high frequency of visceral metastases and worse prognosis." (PMID 35045088, 2022).
breast cancer (continued). "Triple-negative breast cancer (TNBC) is a group of heterogeneous and refractory breast cancers with the absence of estrogen receptor (ER), progesterone receptor (PgR) and epidermal growth factor receptor 2 (HER2)." (PMID 35682800, 2022). "Triple-negative breast cancer (TNBC), which accounts for approximately 15–20% of all breast cancers, is characterized by a lack of estrogen receptor (ER), progesterone receptor (PR) and human epidermal growth factor receptor 2 (HER2)." (PMID 36038948, 2022). "Based on the expression levels of estrogen receptor (ER), progesterone receptor (PR) and human epidermal growth factor receptor 2 (HER2), breast cancer patients could be classified into 4 subtypes: Luminal A, Luminal B, HER2 enriched and triple negative (TN)." (PMID 35342335, 2022). "Accordingly, breast cancers are classified as tumors expressing estrogen receptor-α (ERα/ESR1), progesterone receptor (PGR) and/or epidermal growth factor (EGF) family receptor HER2/ERBB2, which emanate from luminal epithelial progenitors and are classified as luminal-A or -B." (PMID 36171192, 2022). "CDKI therapy is effective in hormone receptor positive (HR+), and human epidermal growth factor receptor two negative (HER2−) advanced breast cancers (ABC) malignancies, but remains susceptible due to estrogen and progesterone receptor overexpression." (PMID 36358806, 2022). "Furthermore, PARP-1 functions are extended in a disease-specific manner; for example, in breast cancer and prostate cancer, PARP-1 binds to estrogen (ER) and progesterone receptor (PR)." (PMID 35158955, 2022). "Triple negative breast cancer (TNBC) is an aggressive subtype of breast cancer characterized by the lack of estrogen receptor, progesterone receptor, and HER2." (PMID 35642054, 2022). "It is well established that estrogen receptor (ER), progesterone receptor (PR), and human epidermal growth factor receptor (HER2) could be regarded as prognostic factors in breast cancer." (PMID 35321515, 2022). "Based on both molecular and histological evidences, BC could be categorized into three subgroups: BC expressing hormone receptor (estrogen receptor (ER+) or progesterone receptor (PR+)), BC expressing human epidermal receptor 2 (HER2+) and triple-negative breast cancer (TNBC) (ER-, PR-, HER2-)." (PMID 35200106, 2022). "In the basal-like subtype breast cancers, they are usually triple-negative, i.e., they lack the estrogen receptor (ER), the progesterone receptor (PR), and the human epidermal growth factor receptor 2 (HER2)." (PMID 36360219, 2022). "Triple-negative breast cancer (TNBC) is an aggressive subtype of breast cancer that does not express estrogen receptor (ER), progesterone receptor (PR), and human epidermal growth factor receptor 2 (HER2) on the cell surface." (PMID 36015303, 2022). "Triple-negative breast cancer (TNBC) is a subtype of breast cancer with the absence of expression of estrogen receptor (ER) and progesterone receptor (PR) together with human epidermal growth factor receptor type 2 (HER2)." (PMID 36505498, 2022). "Triple negative breast cancer (TNBC) is a molecular subtype of breast cancer and is characterized by the absence of estrogen receptor (ER), progesterone receptor (PR), and human epidermal growth factor receptor 2 (HER2)." (PMID 35761256, 2022). "Based on the three biomarkers, estrogen receptor (ER), progesterone receptor (PR), and human epidermal growth factor 2 (HER2), breast cancers are divided into the following three major subcategories: hormone receptor+/HER2−, HER2+, and triple-negative (when none of the three biomarkers is detected)." (PMID 35049580, 2022). "TNBC, the most aggressive breast cancer, does not express estrogen receptor (ER), progesterone receptor (PR), and Her2." (PMID 35743249, 2022).
breast cancer (continued). "This meta-analysis aimed to investigate whether receptor (estrogen receptor [ER], progesterone receptor [PR], and human epidermal growth factor receptor 2 [HER2]) discordances between primary and recurrent breast cancers affect patients’ survival." (PMID 34613502, 2022). "Based on univariate analysis, there were significant differences in stage_N (P = 0.029), histological grade (P = 0.003), ER (P < 0.001), PgR (P = 0.047), Ki-67 (P < 0.001) and HER2 status (P = 0.015) for achieving a pCR in patients with ER-positive breast cancer." (PMID 36605428, 2022). "ER controls the expression of multiple genes and proteins through genomic and non-genomic pathways, whereas PgR is induced by ER, and PgR-related signal transduction pathways are closely related to the occurrence and development of breast cancer." (PMID 36313626, 2022). "Triple negative breast cancer (TNBC) is a subtype of breast cancer, with estrogen receptor, human epidermal growth factor receptor 2 and progesterone receptor negative." (PMID 35243562, 2022). "Our previous research findings simulated that heterogeneity among CRCI in breast cancer survivors with estrogen/progesterone receptor negative (ER−/PR−), showing significant damage on EBPM after chemotherapy." (PMID 35211407, 2022). "Triple-negative breast cancer (TNBC) is a particularly aggressive form of breast cancer, characterized by the lack of estrogen receptor (ER), progesterone receptor (PR), and human epidermal growth factor receptor 2 (HER2)." (PMID 36294342, 2022). "It is clinically characterized by the lack of main receptors of breast cancer; estrogen receptor (ER) and progesterone receptor (PR), as well as the amplification of human epidermal growth factor 2 (HER2)." (PMID 35897832, 2022). "Further, we did not classify subtypes of breast cancer, such as estrogen receptor [ER] positive/negative, progesterone receptor [PR] positive/negative, and triple-negative breast cancers, in our analyses because no such information was available to us." (PMID 35729236, 2022). "Triple-negative breast cancer (TNBC), defined by lack of therapeutic targets (estrogen receptor, progesterone receptor, and Her2), is considered to be a form of breast cancer with more aggression and poorer prognosis." (PMID 36443314, 2022). "TNBC is a heterogeneous collection of breast cancers lacking expression of oestrogen receptor (ER), progesterone receptor (PR), and HER2 amplification, the targets which form the basis for major first line therapies in cancer." (PMID 36380366, 2022). "Triple-negative breast cancer (TNBC) is defined as breast cancer in which the genes for estrogen receptor (ER), progesterone receptor (PR), and HER2/neu are not expressed." (PMID 35991627, 2022). "Triple negative breast cancer (TNBC) is a breast cancer subtype characterized by the absence of estrogen receptor, progesterone receptor and human epidermal growth factor receptor 2 expression." (PMID 35056723, 2022). "Methods were tested on breast cancer RNA-seq data and compared with regards to the number of genes identified at various bimodality index (BI) thresholds and ranking of known bimodally expressed genes (ESR1, HER2, and PGR)." (PMID 35639779, 2022). "HER2 + subtype breast cancer, including non-luminal (HER2 + and ER and PgR-) and luminal (HER2+ and ER or PgR-, or both) breast cancer, exhibits a higher risk of recurrence and a poor prognosis." (PMID 36686782, 2022). "Breast cancer is classified by stage, histology, and grade differentiation, and the expression of estrogen receptor (ER), progesterone receptor (PR), and human epidermal growth factor receptor‐2 (HER2/neu) determines the response of breast cancer cells to currently available chemotherapeutic drugs." (PMID 34856073, 2022). "TNBC represents 15–25% of all breast cancers and is characterized by the lack of estrogen receptor (ER), progesterone receptor (PR) and human epidermal growth factor receptor (HER2)." (PMID 36507540, 2022).
breast cancer (continued). "Based on the analysis in breast cancer cells MCF-7, AF1_FFF mutation did not affect the nuclear localization of PGR." (PMID 36199058, 2022). "The triple-negative breast carcinoma (TNBC), accounting for up to 20% of breast carcinomas, is the aggressive molecular subtype of breast cancer, characterized by the absence of ERα, progesterone receptor (PgR), and HER2." (PMID 35719919, 2022). "Based on the expression of estrogen receptor (ER), progesterone receptor (PR), and human epidermal growth factor receptor 2(HER2), there are at least four molecular subtypes of breast cancer: luminal, basal, human epidermal growth factor receptor 2 (HER2)‐enriched, and normal‐like." (PMID 36072578, 2022). "Hormone receptors (estrogen receptor [ER] and progesterone receptor [PR]) and human epidermal growth factor receptor 2 [HER2] status in primary breast cancers (BC) not only provides prognostic information but it is also crucial for deciding on an effective treatment plan." (PMID 34613502, 2022). "Breast cancer patients often have different positive (+) or negative (−) statuses for the Estrogen Receptor (ER), Progesterone Receptor (PR), Human Epidermal Growth Factor receptor 2 (HER2), which are used to define breast cancer subtypes." (PMID 35428183, 2022). "Triple-negative breast cancers (TNBC) are a type of breast cancer characterized by a lack of cell receptors such as ER (estrogen receptor), PR (progesterone receptor), and human epidermal growth factor receptor 2 (HER2)." (PMID 35216264, 2022). "Triple-negative breast cancer (TNBC) is a subtype of breast cancer that does not express estrogen receptor (ER), progesterone receptor (PR) and human epidermal growth factor receptor 2 (HER2)." (PMID 34875483, 2022). "The basal breast cancer subtype is characterized by triple negativity (for ESR1, PgR and HER‐2), expression of EGFR and cytokeratin 5/6 and is a more aggressive subtype; associated with high tumour grade, younger age and poor prognosis, including shorter disease‐free and overall survival." (PMID 35579852, 2022). "Among all breast cancer subtypes, triple negative breast cancer (TNBC) is differentiated from other types of breast cancer by not expressing three receptors, namely the Estrogen receptor, Progesterone receptor and the receptor tyrosine kinase Her2/neu." (PMID 35563174, 2022). "One study suggested that STC1 was positively regulated by desumoylated progesterone receptor in the absence of ligand for the breast cancer cells." (PMID 35273656, 2022). "To test this hypothesis, we examined known bimodal genes that were relevant to disease progression in breast cancer, including ESR1, HER2, and progesterone receptor (PGR)." (PMID 35639779, 2022). "Among them, basal like breast cancer, also named as triple-negative breast cancer (TNBC), exhibits specific pathological characteristics with estrogen receptor alpha (ERα)-, progesterone receptor (PR)- and HER2-, and has more aggressive phenotype and worse prognosis than other subtypes." (PMID 36450706, 2022). "In the molecular classification of breast cancer, triple-negative breast cancer (estrogen receptor [ER]/ progesterone receptor/human epidermal growth factor receptor-2 [HER2] negative) has a poorer prognosis than other types of breast cancer." (PMID 35473583, 2022). "Triple‐negative breast cancer (TNBC), accounting for 15%–20% of breast cancer (BC) population, lacks hormone receptors (estrogen receptor [ER] and progesterone receptor [PR]) expression and Her2 amplification/overexpression." (PMID 36536485, 2022). "TNBC accounts for 10%-20% of breast cancer and characterized by the lack of traditional therapeutic targets, including estrogen receptor, progesterone receptor, and ErbB-2/HER-2/neu." (PMID 35992877, 2022). "Triple-negative breast cancer is defined as breast cancer that is immunohistochemically negative for estrogen receptor (ER), progesterone receptor (PR), and human epidermal growth factor receptor 2 (HER2)." (PMID 36092784, 2022).
breast cancer (continued). "The TrkA/CD44v3 complex formation rate and activity level appeared higher in breast cancer cell lines, representing various breast cancer subtypes that did not express the progesterone receptor (PR)." (PMID 35346305, 2022). "Pathogenesis and classification of breast cancer is based on the presence or absence of estrogen receptor alpha (ER), progesterone receptor (PR), and human growth factor‐neu receptor (HER2)." (PMID 35671075, 2022). "Compared to luminal breast cancer subtypes, ZEB1 is highly expressed in triple-negative breast cancers, which express neither ERα nor progesterone receptor (PR), which is encoded by an ERα target gene." (PMID 35440541, 2022). "Triple-negative breast cancer (TNBC) is a subset of breast cancer without the expression of estrogen receptor (ER) and progesterone receptor (PgR) and without the overexpression or gene amplification of human epidermal growth factor receptor 2 (HER2)." (PMID 35462552, 2022). "The lack of breast cancer molecular subtypes (estrogen receptor, progesterone receptor, and human epidermal growth factor receptor 2 status) and cancer stages prevented performing a more refined analysis." (PMID 35864141, 2022). "Triple-negative breast cancer (TNBC) comprises 10–15% of all breast cancers and is characterized by the lack of estrogen receptor (ER), progesterone receptor (PR), and human epidermal growth factor receptor (HER-2)." (PMID 36499246, 2022). "The patient underwent a CT-guided needle biopsy of the kidney and lung lesions; pathological examination revealed that both organs contained lesions resembling primary breast cancer that were ER positive, PgR positive and HER2 negative." (PMID 35038044, 2022). "Triple-negative breast cancer (TNBC) is an aggressive subtype of breast cancer with a phenotype demonstrating a lack of estrogen receptor (ER), progesterone receptor (PR) and human epidermal growth factor receptor 2 (HER-2)." (PMID 33916118, 2021). "Triple-negative breast cancer (TNBC) is a particular type of breast cancer defined by the absence of estrogen and progesterone receptor expression as well as the absence of ERBB2 amplification, which accounts for 15% to 20% of breast cancers." (PMID 34422088, 2021). "Triple-negative breast cancer (TNBC), which accounted for 15%–20% of all breast cancer patients, was a kind of breast cancer that lacked expression of estrogen receptor, progesterone receptor, or human epidermal growth factor receptor type 2 (HER2)." (PMID 34580591, 2021). "The ER− breast cancers usually belong to the triple negative breast cancers (TNBC) since the epithelial breast cancer cells, which do not express the estrogen receptor, often do not express the progesterone receptor and the Her2 protein." (PMID 33562506, 2021). "E.g. breast cancer is not subdivided according to the status of estrogen-receptor, progesterone-receptor, HER2 or BRCA1." (PMID 34174885, 2021). "Triple-negative breast carcinoma (TNBC), is an aggressive molecular subgroup of breast cancer characterized by the absence of estrogen receptor alpha/progesterone receptor (ERα/PR) expression and HER2 (ER/PR/HER2-negative)." (PMID 33572395, 2021). "TNBC is a heterogeneous and aggressive form of breast cancer in which the cells do not express estrogen receptor α (ERα), progesterone receptor (PR), or HER2." (PMID 33968766, 2021). "Among them, triple-negative breast cancer (TNBC) is a particularly aggressive subtype of breast cancer, defined by the lack of expression of estrogen receptor (ER), progesterone receptor (PR), and human epidermal growth factor receptor 2 (HER2)." (PMID 35008285, 2021). "This subtype of breast cancer is characterized by a lack of estrogen receptor, progesterone receptor, and HER-2 and accounts for around 15% of breast cancers." (PMID 34638451, 2021).